VIM (vimentin)
Diseases named in the same sentence as VIM in open-access papers (continued):
Sharing a sentence is not in itself a finding about the gene and the disease.
tumor (continued). "Interestingly, host cell expressions of several markers were strongly upregulated towards the tumour bulk, but hardly visible outside the tumour region, including Vimentin and the angiogenic factors Angiopoietin 2, VEGF and FGF2." (PMID 28173797, 2017). "However, the mRNA level of VIM gene was increased in low tumor grade (I-III) and was decreased (silenced or suppressed) in high tumor grade (III-X)." (PMID 28900381, 2017). "Interestingly, E-cadherin expression was decreased (P = 0.006) and vimentin expression was generally increased (P = 0.393) in post-treatment tumor tissue compared to in matched baseline tissues." (PMID 29228662, 2017). "Our data indicate that the process of EMT may be identified in situ on a tumor tissue and this observation, based on application of vimentin and stemness/pluripotency related markers." (PMID 28231820, 2017). "VIM has also been associated with signaling transduction and has been proposed to transfer information from the ECM to the nuclei, which is an important step in the EMT that leads to loss of cellular adhesion and invasion of tumor cells." (PMID 28333958, 2017). "EMT is defined as the transformation of epithelial cells into spindle cells with the loss of membrane E-cadherin expression and the gain of mesenchymal markers such as vimentin, which promotes tumor initiation, progression and metastasis in human mammary epithelial cells." (PMID 28423362, 2017). "Recent findings indicate that vimentin is not only a passive marker of carcinoma, but may also induce changes in cell shape and adhesion, as well as cell invasion of tumor cells." (PMID 28117759, 2017). "Similarly, glioblastoma CTCs isolated from patients as well as from a PDX mouse model, when compared with their matched parental tumor, show the upregulation of RNA encoding for the mesenchymal genes SERPINE1, TGFB1, TGFBR2, and vimentin." (PMID 28544498, 2017). "E-cadherin expression is a hallmark of EMT; reduced expression of E-cadherin is regulated by the expression of mesenchymal neural cadherin (N-cadherin) and vimentin, which alter tumor cell adhesion and motility, and thereby induce changes in morphology and invasive ability." (PMID 28829837, 2017). "Because EMT activation results in tumor cell migration and invasion, our group measured levels of the E-cadherin and vimentin, which are markers for epithelial and mesenchymal, in cells transfected with control or RUNX3 plasmids or control siRNA or RUNX3 siRNA." (PMID 29254144, 2017). "Vimentin and fibronectin expression were changed in tumor tissues." (PMID 28900381, 2017). "Besides, we detected the expression levels of β-catenin, E-cadherin, N-cadherin, and vimentin in NSCLC tumor." (PMID 29054966, 2017). "Consist with the results obtained from the in vitro study, immune-histochemical analyses demonstrated that the expression levels of EZH2, H3K27me3, MMP2, Vimentin, N-cadherin, ki-67 and Cyclin D1 were downregulated in tumor specimens from the GSK343-treated group." (PMID 29228694, 2017). "The mechanisms underlying the anti-tumor effect of EA might be due to EA can induce cell cycle arrest, inhibit the expression of COX-2, NF-κB, Vimentin and induce the expression of E-cadherin." (PMID 28135203, 2017). "Evidence suggests that the epithelial-mesenchymal transition (EMT) (characterized by downregulation of epithelial markers such as E-cadherin and ZO-1, and upregulation of mesenchymal markers such as Fibronectin and Vimentin) is a crucial event in tumor invasion and metastasis." (PMID 27412382, 2016). "Finally, in the experimental mouse model, we showed that curcumin inhibited HGF-stimulated tumor growth and induced an increase in E-cadherin expression and a decrease in vimentin, CD34, and vascular endothelial growth factor (VEGF) expression." (PMID 27525306, 2016).
tumor (continued). "Moreover, NKX6.3 directly bound to promoter regions of SNAI2 and VIM and reduced mRNA transcripts of the SNAI2 and VIM genes, which are important for behavioral changes related to the adhesion and migration properties for local tumor invasion." (PMID 27333045, 2016). "Specifically, the ratio of epithelial markers (e.g., E-cadherin) and mesenchymal markers (e.g., β-catenin, snail, slug, and vimentin) may determine adhesion, polarity, and invasive characteristics of cancer cells, dictating tumor metastasis." (PMID 27447565, 2016). "Tumor cells were positive for vimentin, HHF35, α-smooth muscle actin and factor XIIIa." (PMID 26855713, 2016). "The high level of vimentin expression in the Hi-Myc derived tumor cell lines may allow further dissection of its role in tumor growth and progression." (PMID 26910370, 2016). "Among the most potential diagnostic biomarkers for CRC, the tumor specific M2 isoform of pyruvate kinase (PKM2) and tissue inhibitor of matrix metalloproteinase 1 (TIMP1), vimentin (VIM) and septin 9 (SEPT9) take a lead in being the most extensively investigated ones." (PMID 27844020, 2016). "Vimentin is a filamentous protein that controls cell shape changes during epithelial-mesenchymal transitions (EMT), and are strongly associated with cell invasion and poor tumor prognosis." (PMID 26729407, 2016). "Tumor cell lines derived from xenografts also retained cytokeratin 5 expression suggesting the presence of tumor cells with epidermoid differentiation, along Vimentin expression, which are commonly observed in MEC." (PMID 27285758, 2016). "It was noticed that vimentin expression was increasing significantly with high grade of the tumour." (PMID 27190522, 2016). "Finally, we found that overexpression of ANG2 resulted in changes in the expression of tumor formation-related proteins including vimentin, E-cadherin, Bim, PUMA, Bcl-2, Bax, Cyclin D1, PCNA and CD31." (PMID 27492854, 2016). "Tumor cells expressing Vimentin and α-actin can adapt to the capillary diameters, but cells still expressing cytokeratins might burst." (PMID 27018053, 2016). "More interestingly this study investigated a possible blood based epigenetic biomarker, methylated vimentin, and suggests that baseline circulating levels of tumor methylation may represent a prognostic and/or predictive biomarker." (PMID 27542211, 2016). "Furthermore, the expression levels of CD163 in tumor cells (P = 0.001), vimentin both in tumor (P = 0.006) and at the tumor invasion front (P = 0.002) had a worse prognostic impact on the survival rate." (PMID 26769084, 2016). "The common murine CRC model with a mutation in Apc (Apcmin) exhibits vimentin expression in intestinal adenomas 38; therefore, crossing the vimentin KO and Apcmin mice is expected to produce hybrid mice that are more sensitive to the tumour‐suppressing effect of butyrate than Apcmin mice." (PMID 27072512, 2016). "In addition, the tumor recurrence rates of high-vimentin group were significantly higher than that of those with low vimentin (P = 0.002)." (PMID 26824421, 2016). "Moreover, as a sign of active EMT, we found an increased cytoplasmic reactivity for vimentin and a prevailing nuclear Twist 1 and Slug 1 expression in tumor cells, especially at the tumor’s advancing edge." (PMID 27871286, 2016). "To understand whether there are any crosstalks between Gli1 regulating and EMT or not, we first examined the expression of EMT markers (E-cadherin, vimentin) in the tumor tissues by qRT-PCR and divided the patients into low level and high level." (PMID 27863385, 2016). "The data we obtained from primary tumor xenografts and from the primary cell lines from which the tumors were grown, suggest that some tumors can express epithelial markers such as CD44v8-10 protein alongside mesenchymal markers such as vimentin." (PMID 27253518, 2016).
tumor (continued). "In addition, our findings are confounded by the role of increased methylated vimentin as both a marker of tumor burden and likely also a marker of tumor cytotoxicity." (PMID 27542211, 2016). "Inoculated tumor tissue section were partially stained for Vimentin." (PMID 27351128, 2016). "Redistribution of E-cadherin and strong up regulation of ZEB1 and Vimentin were observed in the surviving tumor; indicative of epithelial to mesenchymal transition (EMT), a mechanism that could contribute to tumor resistance." (PMID 27460820, 2016). "Additionally, many such tumors exhibited evidence of the epithelial to mesenchymal transition (EMT) phenotype as determined by the expression of vimentin in the tumor cells." (PMID 27623078, 2016). "By DEPArrayTM sorting, precise numbers (mean = 133, median 98, range = 5–600) of pure homogenous cells from the major populations of tumor and contaminant diploid stromal cells, as well as other minority putative tumor cells positive for both keratin and vimentin (K + V + ), were recovered." (PMID 26864208, 2016). "A small proportion of transplanted neurosphere cells expressed glial fibrillary acidic protein (GFAP) or vimentin, markers of more differentiated cells, but this number increased significantly during tumor growth, indicating that these cells undergo differentiation in vivo." (PMID 26659251, 2016). "We stained the 20 BRG1-negative and 20 (matched for tumor type) BRG1-positive tumors for E-cadherin and Vimentin expression and found that BRG1 loss was correlated with a loss of E-Cadherin expression and an increase in Vimentin expression by IHC." (PMID 27486753, 2016). "Remarkably, haematoxylin and eosin and immunofluorescence (IF) staining for Vimentin/E-Cadherin revealed that, in Ptenpc−/−; Trp53pc−/− mice treated with PF-03084014, tumour grade and percentage of invasive glands was significantly reduced when compared with Ptenpc−/−; Trp53pc−/− control mice." (PMID 27941799, 2016). "In addition, circulating methylated vimentin adjusted for radiographic tumor bulk correlated with a higher likelihood of obtaining stable disease." (PMID 27542211, 2016). "Also our data suggest the expression of CD163 in tumor cells was significantly correlated with the expression of E-cadherin and vimentin." (PMID 26769084, 2016). "Vimentin positivity was increasing according to increased grade of the tumour and CK positivity; though statistically insignificant, it was decreasing among increased grades of the tumour." (PMID 27190522, 2016). "In addition, decrease of E-cadherin and increase of Vimentin allow tumor cells easily to escape from the origin and metastasize." (PMID 27793002, 2016). "Furthermore, the correlations between miR-652 and E-cadherin (r = 0.9106)/N-cadherin (r = −0.7309)/Vimentin (r = −0.8416)/MMP-2 (r = −0.8971) in primary tumor mass were further identified." (PMID 26498682, 2015). "Vimentin, N-cadherin and E-cadherin have essential roles in the invasion of tumor cells." (PMID 25777142, 2015). "Immunohistochemically, the tumor cells were positive for prolactin, chromogranin-A, and synaptophysin, but were negative for glial fibrillary acidic protein, S-100 protein, epithelial membrane antigen, and vimentin." (PMID 26228535, 2015). "However, the expression of vimentin was found to localize in both tumor and mesenchymal cells in the NCI-N87-R xenograft tumors." (PMID 25669984, 2015). "In vitro, the acquisition of vimentin increases tumor cell invasiveness." (PMID 26594799, 2015). "Heterogeneity is often controlled by driver mutations present i.e. micropapillary (and cribiform/microglandular) pattern relates to metastatic potentiality and vimentin is usually positive in tumour cells; this antibody is also convenient to report sarcomatoid/pleomorphic carcinomas in biopsies." (PMID 26316886, 2015).
tumor (continued). "In addition, multivariate analysis showed that vimentin expression (HR, 2.008; 95% CI, 1.191–3.384), tumor status (HR, 1.830; 95% CI, 1.049–3.194) and lymph node metastasis (HR, 5.77; 95% CI, 2.221–15.028) were independent predictors of mortality in ESCC." (PMID 26095281, 2015). "We found that tumor cells expressed KAI1, E-cadherin, and vimentin protein to be independently associated with nodal metastasis and the co-expression of E-cadherin and vimentin and expression of KAI1 in tumor cells to be significantly associated with NSCLC patient prognosis." (PMID 26231404, 2015). "Immunohistochemical stains revealed the tumor to be positive for vimentin." (PMID 25838959, 2015). "Consideration must be given to Vimentin specific binding epitopes otherwise a misdiagnosis of the patients' tumor samples may result." (PMID 25944973, 2015). "To determine whether responsive tumors may belong to the late TGF-beta signature subgroup we assessed the expression of c-MET at baseline, Vimentin being detected at similar levels across all control tumor samples." (PMID 26057634, 2015). "Importantly, we also found decreased CD44 expression, with altered EMT markers for the decreased vimentin and increased E-Cadherin in the tumor with salinomycin treatment compared to those from control group." (PMID 25483103, 2015). "Furthermore, both in vitro functional assays and an in vivo animal model demonstrated that AOC4P suppresses tumor growth by reducing cancer cell proliferation, migration and invasion ability at least in part by suppressing vimentin expression and the EMT." (PMID 26160837, 2015). "We tested the epithelial mesenchymal transition (EMT) phenotypes that are associated with cancer progression and metastasis in tumor samples from the BaP-treated A/J mice, and found that the expression of E-Cadherin was down-regulated, while N-Cadherin, Vimentin, Slug and Snail were up-regulated." (PMID 26565418, 2015). "Vimentin expression, on the other hand, showed an opposite pattern, where it was overexpressed at the invasive front of the tumour and downexpressed within the tumour centre." (PMID 26146569, 2015). "Most tumor cells showed expressons for vimentin, BAF47 (INI-1), and myogenin." (PMID 26208724, 2015). "Our IHC results show that the majority of tumor cells in SKOV3/pcDNA3.1-CTHRC1 xenografts expressed a more intense vimentin signal, but exhibited weaker E-cadherin staining, two key markers for tumor metastasis, indicating that these cells were undergoing the EMT process." (PMID 26452130, 2015). "Nef-M1 treated tumor cells analyzed via western blot displayed increased expression of the epithelial signature E-cadherin and decreased expression of the mesenchymal signature vimentin, fibronectin, and p-GSK-3β." (PMID 26318034, 2015). "In addition, ZEB2 was also reported to upregulate mesenchymal markers, which include N-cadherin and vimentin, as well as facilitate tumor cell invasion." (PMID 25945841, 2015). "During this process, tumor cells lose expression of specific epithelial markers including E-cadherin, EpCAM, and cytokeratin, and gain expression of mesenchymal cytoskeletal and adhesion proteins such as vimentin and N-cadherin." (PMID 26497689, 2015). "Tumour cells expressed inhibin (3/5) and vimentin (3/5) in 60% of cases." (PMID 26201545, 2015). "However, irregular tumor invasion with a decreased E-cadherin expression and an increased Vimentin expression were observed in tumors induced by KYSE30-shTIP30 cells." (PMID 25544767, 2015). "Moreover, the cells in the tumours formed from miR-137 over-expressing cells induced the epithelial marker E-cadherin expression but mesenchymal marker, Vimentin expression was reduced compare to control." (PMID 26215676, 2015). "Finally, we performed IHC staining on serial tumor sections to investigate inverse regulation of KLK6 and Vimentin as well as intracellular accumulation of β-catenin in tumor cells with KLK6low expression levels." (PMID 25990935, 2015).
tumor (continued). "The tumor was positive for vimentin and focally positive for CD68 and P63." (PMID 25838959, 2015). "EMT is a process that exerts influence on many molecular, such as TGF-β, E-cadherin, N-cadherin Vimentin, ZEB-1, SMAD-2, SMAD-3, SMAD-7, GLI1 and GLI2; these molecules are closely associated with typical phenotype changes of EMT in tumor cell growth and metastasis." (PMID 25895132, 2015). "Notably, cells from non-tumor samples were frequently double positive for cytokeratin and vimentin in 3D cultures with both scaffold types despite the presence of few double positive cells observed in the parental sample." (PMID 26317980, 2015). "Therefore, it is important to evaluate the role of cell adhesion molecules like β-catenin and E-cadherin along with vimentin in tumour metastasis of OSCC." (PMID 25047112, 2014). "Vimentin expression was detected in the tumor stroma region and the tumor cells and varied widely." (PMID 24816558, 2014). "The tumor spindle cells were positive for vimentin, CD68, CD45, and Ki-67 (labeling = 18%)." (PMID 25379319, 2014). "However, the metastatic tumor cells were only moderately stained for vimentin and the Ki-67 labeling indices were <5% in the two tumors." (PMID 24765153, 2014). "Furthermore, in the immunohistochemistry assays, tumor cells were positive for vimentin, CD34 and CD31 expression and negative for the epithelial membrane antigen (EMA)." (PMID 24932310, 2014). "Vimentin was expressed in all tumor specimens, consistent with their mesenchymal lineage." (PMID 24670249, 2014). "Presumably, a treatment that reduces vimentin expression, such as G6, may result in decreased tumor growth, decreased metastatic potential, increased sensitivity to temozolomide, and improved patient prognosis." (PMID 25162558, 2014). "Especially in these tumour cells in addition to E-Cadherin, vimentin and Ki67 is highly expressed." (PMID 24663399, 2014). "The phenomenon of EMT in tumor cells often leads to decreased cell adhesion and increased mobility, and this transition is accompanied by decreased E-cadherin expression and increased expression of N-cadherin, vimentin and other mesenchymal biomarkers." (PMID 24505377, 2014). "We demonstrated that ACCS-M GFP cells exhibited a loss of E-cadherin and integrins and a gain in vimentin, suggesting that the epithelial-mesenchymal transition (EMT) is a key event in AdCC metastasis that induces tumor cell dissemination from the primary tumor site." (PMID 24504414, 2014). "We also found that miR-378 can inhibit tumor growth and invasion partly by targeting vimentin." (PMID 24555885, 2014). "Also numerous vimentin positive cells were seen in control tumor sections, the number of which decreased sharply in Sac-1004 group." (PMID 24811731, 2014). "However, in the pyogenic granuloma portion, CD34 was almost negatively detected, whereas vimentin and Ki-67 were highly detected in the fibroblast-like tumor cells." (PMID 24934284, 2014). "For each tumor, snail expression was plotted versus the expression of E-cadherin and Vimentin." (PMID 24816558, 2014). "Considering the converging data suggesting a role for the EMT during cancer progression, in this study, we initiated an exhaustive screening of 140 clinical samples of ICC to detect links between E-cadherin, Vimentin, snail, slug, β-catenin and tumor progression status." (PMID 24816558, 2014). "Next, a portion of each tumor was subjected to anti-vimentin immuno-histochemistry." (PMID 25162558, 2014). "It has been observed that NSCLC adenocarcinoma is a more mesenchymal-like tumor type, since it has been observed that vimentin, a marker of mesenchymal cells, was overexpressed in well differentiated adenocarcinomas and in the H23, A-549 and HCC-44 cell lines, but not detected in SCC tissues." (PMID 25003366, 2014). "Immunohistochemically, the tumor cells were positive for S-100 protein, vimentin and Melan-A." (PMID 24348822, 2014).